SIRT1 (sirtuin 1)
Diseases named in the same sentence as SIRT1 in open-access papers (continued):
Sharing a sentence is not in itself a finding about the gene and the disease.
Anxiety (continued). "Overexpression of the deacetylase Sirt1 activates MAO-A and decreases intracerebral 5-HT levels in PTSD model animals, but acupuncture was also reported to reverse this trend and alleviate anxiety behavior." (PMID 37200784, 2023). "In this study, we found that Sirt1 knockout (CKO) mice have reduced activity, increased anxiety and decreased spatial learning and memory, compared to CTL mice." (PMID 34867800, 2021). "Given the global effects of NAD+ and SIRT1 on human physiology and function, NAD+ levels can influence anxiety, exploratory and depressive behaviour, and the brain reward system linked to addiction." (PMID 32423100, 2020). "Local overexpression of activated SIRT1 in the ovBNST reversed anxiety behaviors in these mice, decreased CRF upregulation, and normalized the overactive CRF neurons." (PMID 39698215, 2024). "Similarly, Res has been reported to exert neuroprotective effects and reduce anxiety-like behavior through mechanisms involving the HPA axis, inhibition of pro-inflammatory factors, and modulation of Sirt1." (PMID 38684734, 2024). "Additionally, RES impacts the SIRT1/NHLH2/MAO-A pathway, which is known to enhance anxiety-like behavior." (PMID 39335576, 2024). "According to the ROC curve analysis, the area under the curve (AUC) values of PD with anxiety and EDS based on plasma SIRT1 levels were 0.685 and 0.694, the sensitivity values were 65.6% and 90%, the specificity values were 68.7% and 44.7%, and the cutoff values were 39.20 and 49.13, respectively." (PMID 37718350, 2024). "In this last report, the authors used single miR-132 and combined miRNA-132/212 depletion and showed, in both cases, altered expression levels for hippocampal SIRT1 and PTEN-2; two proteins known as targets of miR-132 that are involved in the modulation of anxiety-like behaviors." (PMID 37298523, 2023). "Open field test (OFT) and Morris Water Maze (MWM) test revealed that hippocampal Sirt1 knockdown significantly weakened spatial learning and memory of mice without effect on anxiety and exploratory behavior." (PMID 35668361, 2022). "We have previously demonstrated that SIRT1 induces Mao-A expression, by deacetylating and thus activating its transcriptional activator—NHLH214, which inadvertently results in diminished serotonin levels, and anxiety-like behavior." (PMID 32499508, 2020). "One such mechanism could involve the SIRT1/NHLH2/MAO-A pathway, in which SIRT1-induced deacetylation of NHLH2 transcription factors leads to increased MAO-A expression and decreased 5-HT levels in neurons, potentially exacerbating anxiety-like behaviors." (PMID 40427023, 2025). "One is that the knockout of SIRT1 from EGP cartilage, which affected bone mineralization and maturation, affected the level of osteocalcin (OC) and its un-carboxylated form (GluOC); the latter was shown to serve as a link between bone and brain function, especially anxiety." (PMID 34867800, 2021). "The present study, along with our previous research that showed increased nuclear SIRT1 activity after CVS12,13, indicate SIRT1 activity and cellular localization in the dentate gyrus is dependent upon stress conditions, and importantly SIRT1 activity rapidly modulated mouse anxiety behaviors." (PMID 30271963, 2018). "The implication of rapid effects of cytosolic SIRT1 in CVS and anxiety behavior regulation has not yet been studied." (PMID 30271963, 2018). "While SIRT1 overexpression did not significantly amplify anxiety-like behaviors in morphine-exposed mice, collective data suggest BLA-specific SIRT1 overexpression potentiates morphine-induced anxiety-like phenotypes, potentially limited by OFT’s sensitivity for anxiety assessment." (PMID 40621197, 2025).
melanoma (67 papers, 2011 to 2025). A malignant, usually aggressive tumor composed of atypical, neoplastic melanocytes. "SIRT1 overexpression was initially associated with vemurafenib resistance in BRAFV600E melanoma, and SIRT1 mediated MITF-induced melanoma proliferation." (PMID 39935431, 2025). "Among down-regulated genes, the analysis showed several experimentally validated target genes, such as E2F7, MAP2K1 (also known as MEK1), CCNG1, HMGB2, SIRT1, belonging to key signaling pathways frequently associated to melanoma." (PMID 33670365, 2021). "We find an increased activity of SIRT1 in PLX4032 resistant BRAFV600E-mutated melanoma cells compared with their sensitive counterpart, thereby linking SIRT1 to drug resistance and poor prognosis in melanoma." (PMID 24742694, 2014). "We next determined the underlying mechanisms by which SIRT1 suppression caused cessation of cell proliferation in melanoma cells." (PMID 24742694, 2014). "We next thought to determine the activity of SIRT1 in BRAFV600E-mutated WM9 melanoma cells sensitive (WM9S) to PLX4032 and in their resistant counterpart (WM9R)." (PMID 24742694, 2014). "Most importantly, SIRT1 inhibition rescues the sensitivity to PLX4032 of the resistant BRAFV600E-mutated melanoma cells." (PMID 24742694, 2014). "SIRT1 over-expression relieves the senescence-like phenotype and the proliferation arrest caused by MITF suppression, demonstrating that SIRT1 is an effector of MITF-induced proliferation in melanoma cells." (PMID 24742694, 2014). "Our results reveal that SIRT1 activity is higher in PLX4032-resistant BRAFV600E-mutated melanoma cells compared with their sensitive counterpart." (PMID 24742694, 2014). "Isoform antagonism is especially pronounced in the context of melanoma, as SIRT1 associates with chemokine-rich CD8+-high niches and reinforces responses to PD-1 blockade, while SIRT7 triggers the IRE1α–XBP1 stress pathway to upregulate PD-L1 and promote immune evasion." (PMID 41425553, 2025). "Elevated autophagy accompanying melanoma progression has been associated with loss of galectin-3, increased levels of sirtuin 1 (SIRT1), SIRT6, BNIP3, and long non-coding RNA ZNNT1, and enhanced activity of signaling pathways such as AKT, independent of the mutational status of BRAF." (PMID 32340261, 2020). "Similarly, Ohanna and coworkers reported SIRT1 overexpression in resistant BRAFV600E-mutated melanoma cells." (PMID 29383100, 2017). "In that context, we demonstrate that inhibition of SIRT1 with genetic or pharmacological approaches additively enhances the efficacy of PLX4032 of melanoma cells but more importantly that it rescues the sensitivity to PLX4032 of the resistant BRAFV600E-mutated melanoma cells." (PMID 24742694, 2014). "SIRT1 inhibition by sirtinol or EX-527 re-sensitized resistant BRAF-mutant melanoma cells to vemurafenib, and it was shown that SIRT1 downregulation promotes senescence, while upregulation promotes proliferation." (PMID 39935431, 2025). "The pharmacological inhibition of SIRT1 reduces melanoma cell growth, suggesting its therapeutic potential." (PMID 40573249, 2025).
melanoma (continued). "In summary, our study not only illustrates the mechanism by which USP22 controls melanoma metastasis and ferroptosis through the SIRT1/PTEN/PI3K axis but also provides a basis for the treatment of melanoma metastasis by targeting USP22." (PMID 39135915, 2024). "In this context, our data clearly showed that topotecan impairs the PI3K/Akt pathway and EMT through the USP22/SIRT1/PTEN axis in melanoma." (PMID 39135915, 2024). "Consistently, topotecan treatment decreased SIRT1 expression, phosphorylation of Akt at Ser473 and mTOR at Ser2448, as well as EMT activity, but had minimal effects in USP22‐deficient melanoma cells." (PMID 39135915, 2024). "Inhibition of CDK2 in melanoma cell lines has been shown to overcome their resistance to BRAF and Hsp90 inhibitors, while BUB1 has been identified as a novel target downstream of SIRT1 in melanoma." (PMID 38023136, 2023). "SIRT1 is involved in tumor initiation, promoting cell proliferation and drug resistance, and it is overexpressed in human melanoma." (PMID 36431795, 2022). "Recently one study in melanoma indicated that inhibition of SIRT1 declines melanoma cell growth and increases their sensitivity to PLX4032." (PMID 36224606, 2022). "It has been reported in melanoma that SIRT1, a nicotinamide adenine dinucleotide (NAD+)-dependent protein deacetylase, induces EMT by accelerating E-cadherin degradation and facilitates melanoma metastasis." (PMID 33451139, 2021). "Immunohistochemical analysis of sirtuin 1 expression in samples obtained from non-melanoma skin cancers and actinic keratosis have shown its overexpression in comparison to normal skin and benign tumors." (PMID 33917352, 2021). "MiR-9 inhibits autophagy via targeting Beclin1 and suppresses the proliferation of malignant melanoma cells by targeting SIRT1." (PMID 34588978, 2021). "In early 2014, three separate studies, including one from our lab, demonstrated the pro-proliferative role of SIRT1 in melanoma." (PMID 33178616, 2020). "SIRT1, SIRT6 and SPHK1 induced EMT by up-regulating autophagy-linked lysosomal degradation of E-cadherin in melanoma and hepatocellular cells via Beclin 1-E-cadherin cascade respectively." (PMID 33425768, 2020). "Further, a downstream target of PI3K, melanocyte inducing transcription factor (MITF), has been found to regulate SIRT1 levels in melanoma cells." (PMID 33178616, 2020). "Previous report on sirtuins in melanoma showed that SIRT1 inhibition decreases melanoma cell growth and rescues the sensitivity to PLX4032 of PLX4032-resistant BRAFV600E-mutated melanoma cells." (PMID 32042336, 2020). "SIRT1 overexpression has been described in many cancers compared to normal tissues, including leukemia, non-melanoma and melanoma skin cancer, prostate, and colon carcinomas." (PMID 31261609, 2019). "In melanoma, SIRT1 was reported to promote EMT by downregulation of E-cadherin and its degradation via autophagy, due to deacetylation of BECLIN-1." (PMID 30761005, 2019). "In another study, our group has demonstrated the role of SIRT1 with DNMT3B co-participation in Mxd1 epigenetic silencing in a mouse melanoma model based on cellular stress." (PMID 31261609, 2019). "Previously, we showed that SIRT1 is expressed in lamellipodium, a membrane protrusion of migrating cells, and is necessary for lamellipodium formation and migration of melanoma cells." (PMID 31242212, 2019). "Previous studies have shown that Sirt1 promotes cell proliferation in malignant glioma cells, melanoma cells, glial progenitor cells, primary porcine aortic endothelial, skeletal muscle precursor cells, endothelial progenitor cells, and so on." (PMID 31881009, 2019).
melanoma (continued). "In this study, we found that SIRT1 expression was high in metastatic melanoma compared with primary melanoma." (PMID 29374154, 2018). "There was a significant enhancement of SIRT1 staining in melanoma metastases, as calculated using Pearson’s χ2 statistical analysis." (PMID 29374154, 2018). "We found a correlation between the level of SIRT1 expression and tumor metastasis in melanoma tissues and studied the potential mechanism responsible for the SIRT1-mediated metastatic effect." (PMID 29374154, 2018). "A higher level of SIRT1 protein was found in 87.5% (35/40) of melanoma metastases, whereas 60% (24/40) of primary melanoma samples exhibited an elevated protein level." (PMID 29374154, 2018). "Initially, we found that SIRT1 expression was frequently elevated in metastatic melanoma compared with primary melanoma." (PMID 29374154, 2018). "Compared with the vector control, SIRT1 overexpression promoted melanoma cell migration and invasion, as indicated by a transwell migratory assay and Matrigel invasion assay, respectively." (PMID 29374154, 2018). "Taken together, our data indicate that SIRT1 promotes E-cadherin degradation by autophagy through deacetylation of Beclin 1 in melanoma cells." (PMID 29374154, 2018). "Our findings support a previous study that demonstrated that SIRT1 is involved in melanoma cell migration and that SIRT1 inhibition prevents melanoma metastasis." (PMID 29374154, 2018). "Intriguingly, while SIRT1 was shown to regulate c-MYC in Flt3-ITD mutated leukemia, it has been demonstrated to regulate Mxd1 in malignant melanoma." (PMID 30420889, 2018). "To validate that SIRT1 is further upregulated in metastatic melanoma, we analyzed melanoma RNA-sequencing data from the TCGA database and found that the SIRT1 mRNA level was higher in metastatic melanoma (n = 370) than in primary melanoma controls (n = 103)." (PMID 29374154, 2018). "Overexpression of SIRT1 promoted melanoma cell migration and invasion, whereas CQ interrupted the acceleration of migration and invasion of SIRT1-overexpressing cells." (PMID 29374154, 2018). "Considering the fact that sustained stress of melanocytes leads to their malignant transformation and taking into account the potential role of SIRT1 in melanoma progression, this work aimed to evaluate the role of SIRT1 in our melanoma transformation model." (PMID 29383100, 2017). "We found that cryptolepine treatment markedly reduced the levels of SIRT1 protein in melanoma cells." (PMID 28473727, 2017). "To unravel the role of SIRT1 over-expression after anchorage blockade, we aimed to identify novel SIRT1 targets in different stages of melanoma development." (PMID 29383100, 2017). "Sirt1 silencing increased expression of Mxd1 in both cell lines compared to non-silenced cells, pointing to a Mxd1 repression by SIRT1 in melanoma cells." (PMID 29383100, 2017). "Our previous studies have also shown increased SIRT1 expression during the initial phases of melanoma progression." (PMID 29383100, 2017). "For the first time, we show an interaction between SIRT1 and MYC/MAX/MAD network in melanoma progression, highlighting the SIRT1 role in the regulation of important pathways related to cancer." (PMID 29383100, 2017). "Since the chromatin modifier Sirtuin-1 (SIRT1) is a protein attracted to double-stranded DNA break (DSB) sites and can recruit other components of the epigenetic machinery, we aimed to define the role of SIRT1 in melanomagenesis through our melanoma model." (PMID 29383100, 2017). "One report proposed a role for SIRT1 in melanoma and suggested the use of inhibitors (tenovins, EX-527, and sirtinol), either alone or in combination." (PMID 27226812, 2016). "B16F10 mouse melanoma grew more quickly in SIRT1-transgenic mice than in wild-type mice, whereas SIRT1-overexpressing one grew slowly in both mice." (PMID 26992208, 2016).
melanoma (continued). "The major objective of this study was to identify the downstream targets of the class III HDAC SIRT1 in melanoma cells using gel-free proteomics." (PMID 24743044, 2014). "To determine the role of SIRT1 we first assessed SIRT1 activity in melanoma cell lines and in cells freshly isolated from human biopsies, and in normal human melanocytes." (PMID 24742694, 2014). "Accordingly, SIRT1 suppressed melanoma cells displayed an hypophosphorylation of the retinoblastoma protein, and a G0/G1 cell cycle arrest." (PMID 24742694, 2014). "SIRT1 inhibition decreases melanoma cell growth and rescues the sensibility to PLX4032 of PLX4032-resistant BRAFV600E-mutated melanoma cells." (PMID 24742694, 2014). "Employing the nanoLC-MS/MS gel free approach, 1091 proteins were found to be modulated by tenovin-1 inhibition of SIRT1 in human melanoma cells G361." (PMID 24743044, 2014). "The findings gathered in this study not only contribute to better understand the role of MITF in melanoma cells but also provide strong support that targeting SIRT1 is a valuable clinical option to treat malignant melanoma." (PMID 24742694, 2014). "Taken together, our study has identified novel insights into SIRT1 signaling in melanoma by connecting this important protein deacetylase with spindle assembly check point proteins BUB3, BUB1 and BUBR1." (PMID 24743044, 2014). "In conclusion, these results support the idea that SIRT1 plays a role in the resistance to PLX4032 of melanoma cells and that a combination therapy consisting of PLX4032 and SIRT1 inhibitors represents a valuable therapeutic option." (PMID 24742694, 2014). "Collectively, these observations indicate that SIRT1 silencing promotes a cell cycle arrest in melanoma cells of different genetic background." (PMID 24742694, 2014). "This suggests that under the experimental conditions employed in our study, SIRT1 modulates BUB signaling in melanoma cells." (PMID 24743044, 2014). "Here, we employed a gel free quantitative proteomics approach to identify the downstream effectors and targets of SIRT1 in melanoma." (PMID 24743044, 2014). "Using quantitative gel free proteomics, we analyzed the global proteome changes in response to SIRT1 inhibition by tenovin-1 in human melanoma G361 cells." (PMID 24743044, 2014). "In this study, we employed gel-free quantitative proteomics to identify downstream targets of SIRT1 in melanoma." (PMID 24743044, 2014). "Based on these observations, we investigated the impact of SIRT1 suppression in 501mel melanoma cells with specific siRNA, which triggered an efficient SIRT1 inhibition." (PMID 24742694, 2014). "We used IPA software (trial version) to achieve molecular insight into the tenovin-1 mediated SIRT1 inhibition related proteome network in human melanoma cells." (PMID 24743044, 2014). "The goal of this study was to identify the possible downstream targets of SIRT1 involved in melanoma growth and progression." (PMID 24743044, 2014). "The analysis disclosed a significant lower expression of SIRT1 in nevi, benign melanocytic lesions compared with melanomas." (PMID 24742694, 2014). "Here, we observe an increased SIRT1 activity in human melanoma cells compared with normal human melanocytes." (PMID 24742694, 2014). "In conclusion, our results indicate that SIRT1 acts downstream of MITF in the regulation of melanoma cell proliferation." (PMID 24742694, 2014). "In conclusion, we provide the first evidence that inhibition of SIRT1 warrants consideration as an anti-melanoma therapeutic option." (PMID 24742694, 2014).